TIMP1 (TIMP metallopeptidase inhibitor 1)
Diseases named in the same sentence as TIMP1 in open-access papers (continued):
Sharing a sentence is not in itself a finding about the gene and the disease.
melanoma (continued). "Timp1 was shown to confer anchorage-independent growth capability to melan-a melanocytes and render melanoma cells more aggressive when injected into mice." (PMID 23522389, 2013). "MMPs and TIMP-1 modulation - iRF disrupted melanoma cell migration by inhibiting MMPs and enhancing TIMP-1 expression." (PMID 23342114, 2013). "Timp1 present in conditioned medium of melanoma cells rendered melan-a melanocytes anoikis-resistant through PI3-K signaling pathway independently of Akt activation." (PMID 23522389, 2013). "In our model, Timp1 was found in conditioned medium from all cell lines corresponding to different steps of melanoma progression (4C, 4C11- and 4C11+), except in melan-a melanocytes." (PMID 23522389, 2013). "Differential association among Timp1, CD63 and β1-integrins was observed in melan-a melanocytes, 4C pre-malignant melanocytes and 4C11- and 4C11+ melanoma cells." (PMID 23522389, 2013). "In agreement with our previous data, a progressive increase of Timp1 mRNA expression was found in 4C11- and 4C11+ melanoma cell lines, as described for other melanoma cell lines from our model." (PMID 23522389, 2013). "Five from seven metastatic melanoma cells expressed significantly higher levels of TIMP1, and three from seven melanoma cell lines presented increased levels of CD63 compared to primary human melanocytes." (PMID 23522389, 2013). "Overexpression of TIMP-1, -2, and -3 significantly reduces melanoma tumor cell invasion, migration, growth and metastasis, and significantly reduces tumor neovascularization in the several tumor models studied." (PMID 20631829, 2010). "They used adenovirus-mediated gene delivery of TIMP-1, -2, and -3 to melanoma, cervical carcinoma, and fibrosarcoma cell lines." (PMID 15467768, 2004). "We have previously shown that overexpression of TIMP-1, -2 or -3 inhibits vascular smooth muscle and melanoma cell invasion, while TIMP-3 uniquely promotes apoptosis." (PMID 10188875, 1999). "Interestingly, some reports describe the validity of using the tissue inhibitor of metalloproteinases 1 (TIMP-1) protein in melanoma research 12,13." (PMID 40535809, 2025). "Furthermore, we have assessed the expression of the PMEL and Melan-A markers and the S100B and TIMP-1 protein levels in representative blood samples from melanoma patients and healthy controls." (PMID 40535809, 2025). "This goal was completed using a comparison of CMC numbers, including their pre- and post-treatment status, evaluation of PMEL and Melan-A marker expression, and assessment of serum levels of S100B and TIMP-1 proteins in representative blood samples from melanoma patients and healthy controls." (PMID 40535809, 2025). "Given the link between TIMP-1 and enhanced immunogenicity in melanoma, its interaction with CD74 might either bolster its MHC-I/II chaperoning role or compete with MIF, reducing MIF-induced suppressive effects through CD74." (PMID 38777826, 2024). "TIMP1 is an inhibitor of the metalloproteinases family and confers anoikis resistance in melanoma." (PMID 38785271, 2024). "We thus wondered whether active MMP-9, exclusively observed when Tspan8+ melanoma cells were surrounded by keratinocytes, coincided with low levels of TIMP-1." (PMID 32455575, 2020). "However, TIMP-1 was involved in the development of various cancer, such as melanoma, colon, and acute myeloid leukemia, through exerting an inflammatory network in the tumor microenvironment." (PMID 30486830, 2018). "Interestingly, in our melanoma progression model, Timp1 was shown to modulate the PI3K/PDK1 axis, since decreased Timp1 expression and PI3K inhibition attenuated PKD1 phosphorylation along with melanoma genesis." (PMID 28430130, 2017). "We observed previously that Timp1 contributes to melanoma development activating PI3K signaling pathway since wortmaninn and LY inhibit anoikis resistance, a hallmark of cancer, acquired by melanocytes overexpressing Timp1." (PMID 28430130, 2017).
melanoma (continued). "Since the silencing of Timp1 conferred sensitivity to anoikis and reduced the colony formation along melanoma progression, we analyzed whether reducing Timp1 levels would affect tumor growth and lung colony formation in vivo." (PMID 28430130, 2017). "We also demonstrated that Timp1 associates differentially with CD63 and β1-integrins along melanoma progression and that this association may be related to the induction of the PI3K signaling pathway." (PMID 28430130, 2017). "One of the main roles of Timp1 in our melanoma progression model is to confer anoikis resistance." (PMID 28430130, 2017). "In addition, the relevance of Timp1 in apoptosis induced by others factors was evaluated by treating melanoma cells with dacarbazine, a chemotherapeutic drug used in metastatic melanomas." (PMID 28430130, 2017). "In addition, we observed high levels of TIMP1 in five from seven metastatic human melanoma cell lines analyzed." (PMID 23522389, 2013). "Moreover, both PI3-K inhibitor and Timp1-neutralizing antibody decreased anoikis resistance of melanoma cells, suggesting that also in tumorigenic cells survival modulation by Timp1 is regulated by PI3-K signaling pathway." (PMID 23522389, 2013). "In fact, an increase in N-linked oligosaccharides was observed in melanoma cells derived from melan-a subjected to sequential cycles of deadhesion, reinforcing the idea that TIMP1 would confer tumor aggressiveness independent of its function on MMP activity." (PMID 23522389, 2013). "Increasing Timp1 expression rendered melanoma cell more anoikis-resistant and more efficient in metastases development, indicating the correlation between Timp1 and poor prognosis in melanoma." (PMID 23522389, 2013). "Furthermore, the neutralization of Timp1 with a specific antibody reversed the acquisition of anoikis-resistant phenotype by melan-a cells in the presence of conditioned medium from 4C11+ melanoma cells." (PMID 23522389, 2013). "Moreover, increased anoikis resistance conferred by conditioned medium from 4C11+ melanoma cells was abrogated by the presence of Timp1-neutralizing antibody, demonstrating that extracellular Timp1 is important to render melan-a melanocytes anoikis-resistant." (PMID 23522389, 2013). "The association between β1-integrins and TIMP1 was observed in the human metastatic melanoma cells, but not in primary melanocytes." (PMID 23522389, 2013). "In conclusion, our data demonstrate differential interaction among CD63, Timp1 and β1-integrins between normal and melanoma cells and that this binding may regulate essential processes for tumorigenesis such as anoikis resistance." (PMID 23522389, 2013). "A better understanding of how Timp1 modulates anoikis resistance during the melanoma progression may be valuable in developing new therapeutic interventions." (PMID 23522389, 2013). "Moreover, melanoma cells overexpressing Timp1 acquire increased capacity to grow and metastasize in vivo." (PMID 23522389, 2013). "Timp1 was shown to interact with β1-integrins only in 4C11- and 4C11+ melanoma cells." (PMID 23522389, 2013). "Preventing adhesion to the substrate could result in changes in the structure and composition of lipid rafts, glycosphingolipid-cholesterol-enriched microdomains, affecting Timp1/CD63/β1-integrin complex assembly along melanoma development." (PMID 23522389, 2013). "A recent study has shown stimulation of melanoma cell lines by TIMPs, and that during melanoma progression growth responses to TIMP1 and TIMP2 may gradually change." (PMID 15083203, 2004). "Moreover, melanoma cells overexpressing Timp1 acquire increased capacity to metastasize in vivo." (PMID 28430130, 2017). "However, the signaling pathway induced by Timp1 to protect melanoma cells from apoptosis is still unknown." (PMID 23522389, 2013). "In addition, our data points TIMP1 as a biomarker of human melanoma." (PMID 23522389, 2013).
melanoma (continued). "Several studies have shown that melanoma cells can express a specific pool of MMPs (MMP-1, MMP-2, MMP-9, MMP-13, and MT1-MMP) as well as their tissue inhibitors (TIMP-1, TIMP-2, and TIMP-3)." (PMID 39594665, 2024). "TIMP1, through its interaction with beta-1 and CD63, activates the PI3K-AKT pathway, thereby mediating anoikis resistance in melanoma and facilitating tumor progression in ccRCC14,47." (PMID 38802480, 2024). "Primary human and bone-marrow-derived DCs secrete TIMP-1, which notably increases MHC-I expression in classical type 1 dendritic cells (cDC1), especially under melanoma antigen exposure." (PMID 38777826, 2024). "In the presence of TIMP-1, CD63 can interact with integrin β1, forming a TIMP-1/CD63/integrin β1 complex, which leads to malignant progression, as in the case of melanoma genesis." (PMID 37443843, 2023). "For the level of mRNA expression in the TCGA database and melanoma cell lines, SLC39A14, PSMB4, CRELD2, CDKN2A and TIMP1 were higher in SKCM tissues than in normal skin tissues, and NDRG1, ATF3, and JUND had an opposite trend." (PMID 36226170, 2022). "The relative expression level of the hub genes was reverified in melanoma cell lines, and showed that HIF1A, IL1B, HMOX1, MMP3, CDKN2A and TIMP1 were upregulated, while PTEN, PRKCA, ATF3 and BRAF were downregulated in melanoma samples." (PMID 36226170, 2022). "In these cells, altered expression of ADAM9 controls TIMP-1 expression and TNF-α/sTNFR1 pathway leads to modulation of melanoma cells proliferation and apoptosis." (PMID 32906814, 2020). "Nevertheless, overexpression of EphB4 in A375 melanoma cells also influenced expression of 9 angiogenesis-related proteins (Ang-1, VEGF, Akt/PKB, TIMP-1, TIMP-2, TIMP-3, IL-8, TGF-β2, TGF-β R3)." (PMID 33153234, 2020). "The assembly of TIMP-1, CD63, and β1-integrins at the cell surface of melanoma cells was involved in the acquisition of an anoikis-resistant phenotype." (PMID 30486830, 2018). "Our findings demonstrate that Timp1 promotes cell survival with the participation of PDK1 and PKC in melanoma." (PMID 28430130, 2017). "In the present study we show that CoQ0 treatment significantly inhibits melanoma migration and invasion by down-regulating MMP-2, MMP-9 and up-regulating TIMP-1 and TIMP-2 expressions." (PMID 26968952, 2016). "Relative expression of TIMP1 and CD63 in human metastatic melanoma cells was analyzed by real time PCR." (PMID 23522389, 2013). "Our results show that Timp1 is assembled in a supramolecular complex containing CD63 and β1-integrins along melanoma genesis and confers anoikis resistance by activating PI3-K signaling pathway, independently of Akt phosphorylation." (PMID 23522389, 2013). "Despite the increase in Timp1 expression in 4C11- and 4C11+ melanoma cell lines, high MMP activity was found in these melanoma cell lines, suggesting MMP-independent functions of Timp1." (PMID 23522389, 2013). "Melanoma and tumor stromal cells express several MMPs, including MMP-1, -2, -3, -7, -9, -14, -15, -16, as well as tissue inhibitors of MMPs such as TIMP-1, -2, and -3." (PMID 20631829, 2010). "TIMP-1 and -3 were abundantly expressed in the cancer and/or stromal cells of grade III and IV melanomas, while TIMP-2 protein was detected also in melanomas representing lower invasive potential." (PMID 10360651, 1999). "As a methodology, SFD is able to reveal well-known proteins in melanoma exosomes that are immune-related and are also surface-expressed proteins, such as CD26 (DPP4), CD44, CALR, B7-H3 (CD276), CSF1, ICAM1, L1CAM, MICB, APOH, TIMP1, and CD39." (PMID 40805206, 2025). "Additionally, luteolin inhibited proliferation, invasion, and metastasis in A375 melanoma cells by downregulating MMP2 and MMP9 and upregulating TIMP-1 and TIMP-2 expression levels." (PMID 40066127, 2024). "Additionally, TIMP1, integrating with CD63 and β1‐integrins as a complex, confers anoikis resistance by activating PI3K signaling pathway in melanoma." (PMID 36507553, 2023).
melanoma (continued). "In contrast to those of melanomas demonstrating segmental regression, TIMP1 has been observed to be overexpressed in nonregressing components of melanomas with partial regression." (PMID 36975387, 2023). "To evaluate whether there were differences in TIMP1 levels between stage III and IV melanoma patients, we analyzed publically available TCGA data and found no change in TIMP1 mRNA levels." (PMID 31917795, 2020). "By analyzing the dominant ligand-receptor pairs contributing to this spatial organization, we identified that the interactions between CD63 and TIMP1 contributed ~66% to the cellular interaction potential of melanoma malignant cells while HNC cells expressed CD63 and TIMP1 at much lower levels." (PMID 32541867, 2020). "Notably, the previously reported composite cytokine signature in melanoma and the composite cytokine signature identified in the current study share several of the same individual cytokines, such as CRP, TIMP-1, and FRTN, but also include different cytokines." (PMID 31829287, 2019). "We also showed that Timp1 modulates phosphorylation of PDK1 and PKC along melanoma progression." (PMID 28430130, 2017). "Moreover, we have shown that, in human metastatic melanoma cells, Timp1 and CD63 expression are increased and positively correlated with colony formation capability, strengthening the possible role of Timp1 in human melanoma genesis." (PMID 28430130, 2017). "Only the melanoma cell lines 4C11− and 4C11+ were sensitized to cell death via anoikis in the absence of Timp1, as shown by MTT assay and caspase-3 cleavage after adhesion impediment." (PMID 28430130, 2017). "Interestingly, several protease inhibitors, such as TIMP1, TIMP3, and SERPINE2, were also upregulated in metastatic primary melanomas." (PMID 26918341, 2016). "Kluger and colleagues proposed a multiplex, plasma-based protein biomarker panel that included CEACAM, ICAM-1 (intercellular adhesion molecule 1), osteopontin, MIA (melanoma inhibitory activity), GDF-15 (growth differentiation factor 15), TIMP-1 (tissue inhibitor of metalloproteinase 1), and S100B." (PMID 27642217, 2016). "The reduced metastatic ability of tissue inhibitors of metalloproteinase (TIMP)-1 overexpressing melanoma cells is due to micrometastatic colony formation, but not defective extravasation." (PMID 25823820, 2015). "The interaction between CD63 and Timp1 was observed in pre-malignant 4C melanocytes and 4C11- and 4C11+ melanoma cell lines, but not in the parental melan-a melanocytes." (PMID 23522389, 2013). "Soluble Timp1 was found in the conditioned media from pre-malignant 4C, and 4C11- and 4C11+ melanoma cell lines, but not in that from non-tumorigenic melan-a melanocytes." (PMID 23522389, 2013). "In order to check if Timp1 also confers anoikis-resistance in melanoma cells, non-metastatic 4C11- and metastatic 4C11+ melanoma cells were subjected to anchorage blockade for 96 hours in the presence or not of a Timp1-neutralizing antibody." (PMID 23522389, 2013). "Over-expression of the metalloprotease inhibitor TIMP-1 does not block B16 melanoma cell extravasation into lung tissue, but does alter subsequent tumor growth within lung tissue." (PMID 15904519, 2005). "Moreover, TIMP-1 was also added into the BMDC culture in combination with a vesicle-enriched tumor-conditioned media (EV-TCM) from 72-h cultured B16F10 melanoma cells, known for effectively enriching melanoma antigens for MHC-I-mediated CD8 + T cell priming." (PMID 38777826, 2024). "Exploring its roles may lead to enhanced strategies benefiting not just melanoma, but other cancers where TIMP-1 correlates with improved survival." (PMID 38777826, 2024). "Overall, our data show that Tspan8+ melanoma cells surrounded by keratinocytes maintained lower TIMP-1 level when compared to melanoma cells juxtaposed without contacts with keratinocytes, thus favoring proMMP-9 activation by the fully active MMP-3, in a Tspan8-dependent manner." (PMID 32455575, 2020).
melanoma (continued). "In addition, we reported, for the first time, the assembly of a supramolecular complex containing Timp1, CD63, and β1-integrins at the cell surface in melanoma cells, and its involvement in the acquisition of an anoikis-resistant phenotype through the PI3K signaling pathway." (PMID 28430130, 2017). "There is no change in AKT activation in melanoma cell lines silenced for Timp1." (PMID 28430130, 2017). "However, in our model, Timp1 is not involved in AKT activation since decreased Timp1 expression did not affect AKT phosphorylation in melanoma cells." (PMID 28430130, 2017). "Western blot analysis performed after immunoprecipitation with anti-β1-integrin antibody showed interaction between Timp1 and β1-integrin only in the tumorigenic melanoma cell lines (4C11- and 4C11+), but not in non-tumorigenic melan-a or pre-malignant 4C melanocytes." (PMID 23522389, 2013). "Once it was shown that in human breast epithelial cells the interaction among CD63, TIMP1 and β1-integrin can regulate apoptosis, we analyzed the possible differential interaction among CD63, Timp1 and β1-integrin in cell lines corresponding to different stages of melanoma progression." (PMID 23522389, 2013). "The level of serum TIMP-1 in patients with melanoma has previously been shown to be significantly higher than in controls, leading to the speculation that serum level of TIMP-1 may be a new useful marker for melanoma progression." (PMID 23548070, 2013). "Therefore, it is possible to suggest that, in this model, the tight complex comprised by Timp1, CD63 and β1-integrins contributes to the acquisition of malignant phenotype, since the interaction among these three molecules was observed only in melanoma cell lines." (PMID 23522389, 2013). "In addition, our data point TIMP1, mainly together with CD63, as a potential biomarker of melanoma." (PMID 23522389, 2013). "The presence of keratinocytes, irrespective of contacts with melanoma cells, slightly augmented the MMP-9 mRNA levels in keratinocytes and sorely decreased TIMP-1 transcription in invasive melanoma cells." (PMID 32455575, 2020). "The cell lines presenting activated PKC (pre-malignant melanocytes 4C and non-metastatic melanoma cells 4C11−), but not metastatic cells, had reduced PKC activation when Timp1 was silenced." (PMID 28430130, 2017).